FBXW7 (F-box and WD repeat domain containing 7)
Diseases named in the same sentence as FBXW7 in open-access papers (continued):
Sharing a sentence is not in itself a finding about the gene and the disease.
cancer (continued). "Furthermore, FBXW7 knockout promoted increased expression of cancer-promoting factors by M2-like TAMs." (PMID 33260160, 2020). "FBXW7 is the most commonly inactivated ubiquitin-proteasome system protein in human cancer." (PMID 32907612, 2020). "We also speculate about the function of FBXW7 as a key player in the cell fate after DNA damage and how this could be exploited in the treatment of cancer disease." (PMID 32316282, 2020). "Based on the articles reviewed here, it has been proposed that the use of FBXW7 inhibitors together with genotoxic drugs may be a possible approach for cancer treatment, but in-depth studies should be done to prove the therapeutic efficacy of this treatment." (PMID 32316282, 2020). "This could produce pH-sensitive degradation of Myc, with Myc being stabilized specifically at the increased pHi of cancer where His465 of Fbxw7 is more likely to be deprotonated." (PMID 32992762, 2020). "Mice with FBXW7 conditional depletion in the T cell lineages, bone marrow stromal cells could develop cancer." (PMID 33260160, 2020). "The functions of FBXW proteins, like FBXW7, have been well-established in many human cancers." (PMID 32175272, 2020). "Interestingly, FBXW7 expressed in the host microenvironment also suppressed cancer metastasis depending on the FBXW7/NOTCH/CCL2 axis." (PMID 30341246, 2019). "Thus, overexpression of Pin1 can significantly downregulate FBXW7, thereby consequently augmenting cancer cell progression." (PMID 30791487, 2019). "Furthermore, miR-27a directly silences the FBXW7 gene by binding to its 3′ untranslated region (UTR), thereby reducing the expression of FBXW7 in cancer cell." (PMID 31572683, 2019). "Furthermore, some reports suggested that cholesterol—one of the end products of mevalonate pathway—or its metabolite 27-hydroxycholesterol (27-HC) control cancer cell proliferation through downregulation of FBXW7." (PMID 31569395, 2019). "Hence, activation or upregulation of FBXW7 has been indicated to overcome chemoresistance and sensitize the cancer cells to chemotherapies and increased the therapeutic efficacy of the existing treatments." (PMID 30791487, 2019). "It is, therefore, not surprising that loss-of-function of FBXW7 by genomic deletion or mutation, promoter hypermethylation frequently occurs in various human cancers." (PMID 31342282, 2019). "It has been indicated that NF-κB p65 which is upregulated in human bladder cancer cells significantly enhanced the cancer cell migration by stabilizing the activity of FBXW7 which in turn ubiquitylated and induced degradation of RHO guanosine diphosphate dissociation inhibitor (RhoGDI)-α protein." (PMID 30791487, 2019). "Therefore, when focusing on the elimination of all cancer cells, the role of FBXW7 in CRCs is still controversial." (PMID 31067777, 2019). "Moreover, knockdown of FBXW7 in CRC cell lines increased the sensitivity to anti-cancer drugs in vitro and in vivo." (PMID 31067777, 2019). "Its anti-cancer effects are carried out through degradation of several target onco-proteins, including c-Jun, Notch1, c-Myc, and cyclin E. Therefore, cellular regulation of Fbxw7 is an important step in maintaining cellular homeostasis." (PMID 31371703, 2019). "si circ-FBXW7 expression in SW480 and SW620 cells significantly improved the cell proliferation, colony formation, cell migration and invasion, whereas, the overexpression of circ-FBXW7 reversed the changes, which are consistent with FBXW7 functions in regulating the cancer cellular processes." (PMID 31519156, 2019). "Large-scale, broad mutation testing of FBXW7 and KDM3B in individuals with cancer will probably be required to establish the full spectrum of associated cancers, because of the rarity of truncating variants and the challenges in interpreting non-synonymous variation in these genes." (PMID 30885698, 2019).
cancer (continued). "Although the FBXW7 variant is not generally considered actionable, FBXW7 is one of the most mutated genes in cancer and developing sensitivity or resistance information related the variant would be beneficial." (PMID 30709382, 2019). "Increasing evidence shows that the FBXW7 protein could overcome EMT-induced resistance to chemotherapy in malignant tumors." (PMID 30999935, 2019). "Moreover, numerous studies have also shown its role in cancer cell chemosensitization, thereby demonstrating the importance of FBXW7 in the development of curative cancer therapy." (PMID 30791487, 2019). "The hyperexpression of WNT target genes corresponds with the hyperactivated WNT pathway in primary CRC and CRC cancer cell lines, most likely resulting from the biallelic inactivation mutation of APC, FBXW7, AXIN2, and FAM123B or the activating mutations in CTNNB1." (PMID 30363662, 2018). "The tumor suppressor gene FBXW7 modulates chemosensitivity in various human cancers." (PMID 29633504, 2018). "In addition to genetic mutations, other mechanisms involving microRNA, long non-coding RNA, and specific oncogenic signaling pathways can inactivate FBXW7 functions in cancer cells." (PMID 30086763, 2018). "FBXW7 has therefore been characterised as a tumour suppressor in human cancer." (PMID 29386660, 2018). "While cancer cells show decreased levels of Fbxw7 and elevated HSF1 protein levels, pathogenic polyQ-expressing cells and tissues show the opposite: increased Fbxw7 levels and increased CK2-dependent S303/307 phosphorylation of HSF1, which together drives HSF1 degradation." (PMID 28194040, 2017). "Previous studies have reported that FBXW7 can regulate EMT process in several cancer types." (PMID 29097832, 2017). "FBXW7 silencing mediated the chemoresistance of cancer cells." (PMID 29262575, 2017). "Fbxw7 is strongly associated with tumorigenesis, and the mechanisms and consequences of Fbxw7 deregulation in cancers may soon enable the development of novel therapeutic approaches." (PMID 26886596, 2016). "The overall frequency of point mutation is about 6%, while the frequency of deletion is more than 30% across human cancer types, suggesting that disruption of FBXW7 may be a major feature of many human cancers." (PMID 27376155, 2016). "Collectively, these results suggest that FBXW7 inhibits the cancer stem-like capacity of CCA cells." (PMID 25749036, 2015). "Importantly, the role of YAP and FBXW7 in CCA invasiveness was confirmed also in vivo by xenograft models, where YAP overexpression or FBXW7 knockdown led to an increased cancer dissemination." (PMID 26703747, 2015). "FBXW7 might act as a core factor in different mechanisms used by cancer cells to become resistant to chemotherapeutic drugs." (PMID 25860929, 2015). "Finally, we demonstrated that the Fbxw7 gene signatures identified in mouse tumors significantly overlap with FBXW7 co-expressed genes in human cancers." (PMID 26575021, 2015). "A loss of Fbxw7 and subsequent increase in TGIF1 expression has also been implicated in cancer." (PMID 22335355, 2012). "Our results suggest that in addition to mutation, differential expression of FBXW7α AS forms with different translational properties may serve as a novel mechanism for inactivation of FBXW7 in human cancer." (PMID 23166673, 2012). "FBXW7 is inactivated in ∼6% of all cancers across many subtypes." (PMID 21215367, 2011). "This suggests that cancer proliferation and progression driven by FBXW7 mutations are not solely dependent on Wnt/β-catenin signaling and that targeting a single FBXW7 substrate may have limited therapeutic efficacy." (PMID 39749199, 2024). "In addition, miR223 possesses broad regulatory roles for FBXW7 in many cancers." (PMID 38892210, 2024).
cancer (continued). "Previous studies demonstrated that FBXW7 was down-regulated through Akt signaling pathways in cancer cells; however, the intracellular signal transduction cascades that regulate FBXW7 transcription in 3D cancer spheroids with cancer stemness properties currently remain unclear." (PMID 38892210, 2024). "Therefore, K+ channel inhibitors may be useful as novel agents that suppress the CEBPD pathway and may reverse c-Myc-mediated cancer stemness by up-regulating FBXW7." (PMID 38892210, 2024). "Notably, in one recent study, FBXW7 deficiency led to defective DNA damage repair and altered metabolic features, which increased NADPH consumption with enhanced sensitivity to radiotherapy in IDH1 mutant cancer cells." (PMID 37176148, 2023). "Therefore, enhancing the active expression of FBXW7 by targeting upstream regulators could be a novel approach for cancer drug resistance therapy." (PMID 38027013, 2023). "Moreover, FBXW7 can target hypoxia-inducible factor-1α (HIF-1α) for ubiquitin-dependent degradation during hypoxia, which causes metabolic changes and angiogenesis in cancer cells." (PMID 37176148, 2023). "Therefore, the effects of targeting FBXW7 on cancer outcomes are complex." (PMID 37408248, 2023). "Notably, some oncogenic factors could promote cancer development by regulating the dimerization of FBXW7." (PMID 37658431, 2023). "We provide evidence that DYRK2 is involved in FBXW7 stability control in response to DNA damage, with important consequences on cell survival, and rendering cancer cells sensitive to the chemotherapy drug Paclitaxel and anti-cancer BET (Bromodomain and Extra-Terminal motif) inhibitors." (PMID 36934104, 2023). "However, it is still unclear how FBXW7 itself is regulated in different human cancers." (PMID 37408248, 2023). "In summary, FBXW7 could be utilized as a target to improve the sensitivity of immunotherapy or that with the combination of other treatment to benefit patients suffering from cancers." (PMID 35814468, 2022). "Thus, we believe that FBXW7-mediated ERK3 degradation suppresses cancer cell proliferation." (PMID 35022544, 2022). "This suggests that some FBXW7 activity may be required and that a reduction, but not complete loss, of FBXW7 activities may provide stronger anti-cancer therapy." (PMID 35346215, 2022). "Interestingly, FBXW7 has recently been studied as a target gene of miRNAs in various cancers." (PMID 35094292, 2022). "Therefore, a better understanding of the mechanisms of the regulation of FBXW7 expression may be effective in therapy against cancer." (PMID 35064102, 2022). "Both the regulations and degradation functions of FBXW7 have been reviewed above, and we want to further explore whether it is involved in immunity for immunity has a crucial connection with most diseases including cancers." (PMID 35814468, 2022). "FBXW7 itself is transcriptionally downregulated by the NOTCH downstream effector Hes‐5, and therefore, the perturbation of the feedback regulatory loop may be held responsible for the FBXW7 haploinsufficiency as seen for NOTCH‐dependent functions in the cancer stem cells (CSCs)." (PMID 33822486, 2021). "Finally, we propose few future perspectives to further elucidate the role of FBXW7 in regulation of a variety of biological processes and tumorigenesis, and to design a number of approaches for FBXW7 reactivation in a subset of human cancers for potential anticancer therapy." (PMID 34760892, 2021).
cancer (continued). "Importantly, we observed one cancer cell line in which elevated cyclin E1 caused by knockdown of FBXW7 did not appear to activate CDK2 (as measured by pNPM)." (PMID 32076484, 2020). "In addition, the relationship between miR-223 and FBXW7 has been studied in several cancers." (PMID 32577098, 2020). "Therefore, any deletion, mutations, or hypermethylation in the human FBXW7 gene could lower or inactivate FBXW7, resulting in the build-up of oncogenic substrates, which could lead to the formation and progression of various cancers, including CRC." (PMID 32245111, 2020). "However, the clinical significance of Fbxw7 in predicting prognosis and the mechanisms involved in the anti-cancer effects of Fbxw7 are unknown." (PMID 24884509, 2014). "Most patients with FBXW7 mutations had limited benefit from mTOR based therapies; however, studying mTOR inhibitors in cancers lacking simultaneous molecular abnormalities as well as describing functional consequences of specific FBXW7 mutation subtypes warrants further investigation." (PMID 24586741, 2014). "Importantly, the anti-cancer effect of Fbxw7 could be partially inverted by restoring YAP expression in vitro and in vivo." (PMID 24884509, 2014). "Targeting the interaction between FAM83D and FBXW7 could serve as an effective cancer therapy." (PMID 24344117, 2013). "Deletions of chromosome 4q31, on which FBXW7 is located, are common in many types of human cancers, suggesting that disruption of this pathway may be a major feature of many, or even a majority, of human cancers." (PMID 23166673, 2012). "Importantly, mutations in specific isoforms have also been identified in cancers, further strengthening the notion of non-redundant functions for the three different Fbxw7/hCdc4 isoforms." (PMID 21122106, 2010). "The F-Box and WD Repeat Domain Containing 7 protein (FBXW7), a component of Skp1-Cullin1-F-box (SCF) complexes, has been shown to regulate cellular growth and act as a tumour suppressor in several cancers." (PMID 40011575, 2025). "Although several studies have revealed how FBXW7 loses its function in cancer cells, the role of the C‐MYC‐SKP2 loop in human cancer remains confused." (PMID 40051297, 2025). "In vitro, FBXW7 significantly inhibited colony formation, cell cycle progression, cell migration, EMT process, cancer stemness and promotes apoptosis." (PMID 38268032, 2024). "FBXW7-mediated ubiquitination and degradation of SHOC2 block MAPK pathway activation, thereby inhibiting cancer growth signaling." (PMID 39749199, 2024). "Among pluripotency genes that are known as cancer stem cell (CSC) markers, c-Myc is a substrate of FBXW7-mediated protein degradation." (PMID 38892210, 2024). "In detail, BRD9 was located together with other known cancer dependencies, including PIK3R1, EZH2, and FBXW7, whereas SF3B1 had a very high efficacy but low selectivity." (PMID 39261602, 2024).
cancer (continued). "Deletion of FBXW7 leads to the accumulation of the pro-survival factor MCL-1, which confers chemoresistance to cancer cells." (PMID 38027013, 2023). "As noted, the SCF family, which includes FBXW7, SKP2, and β-TrCP, affects various proteins that regulate overall cancer development, which makes it an attractive target to combat cancer." (PMID 37176148, 2023). "Current studies focus on the role of FBXW7 as a bridge between DDR and cancer metabolic reprogramming." (PMID 37176148, 2023). "FBXW7 facilitates NHEJ in a degradation-independent manner via K63-linked polyubiquitination of X-ray repair cross-complementing protein 4 (XRCC4) at lysine 286, implying that inactivating FBXW7 could be a potential strategy for improving the efficacy of radiotherapy in human cancers." (PMID 36694209, 2023). "In contrast, increased proteasomal degradation of FBXW7 protein accumulation and secondary FBXW7 substrate MCL-1 due to TRIP12 inactivation sensitizes cancer cells to antitubulin chemotherapy." (PMID 36998461, 2023). "FBXW7 acts as a tumor suppressor gene in various cancer types, and analysis of patient data demonstrated that GBM patients with higher FBXW7 mRNA levels had significantly better overall survival compared to those with lower levels." (PMID 37752997, 2023). "Further development of compounds that promote FBXW7-mediated CHD6 degradation and inhibit Wnt signaling can be a rational cancer therapy for CHD6-overexpressing cancers." (PMID 36473865, 2022). "CircFBXW7 is derived from the parent gene of F-box and WD repeat domain containing 7 (FBXW7), which participates in the progression of cancer via the ceRNA mechanism and can be translated into protein." (PMID 36117850, 2022). "MiR-27a-3p upregulation has been identified in a variety of human cancers, and miR-27a-3p modulates cancer progression by targeting multiple targets including NOVA1, FBXW7 and BTG2." (PMID 35348441, 2022). "Our study revealed several cancer driver genes that differed between the high and low m5C score groups, including KRAS, FBXW7, and SMAD3." (PMID 35433474, 2022). "Here, we show the correlation of FBXW7 expression with CD4+ T cells, CD8+ T cells, and Tregs infiltration level in multiple cancer types." (PMID 35814468, 2022). "In this way, the substrate of FBXW7, IFNGR1, showed a trend of increasing expression and further promoted the tumorigenesis and metastasis of cancer." (PMID 35814468, 2022). "The ubiquitin ligase adaptor for this complex, FBXW7 (aka FBW7), is one of the most commonly dysregulated UPS proteins in human cancers." (PMID 36293188, 2022). "F-box and WD repeat domain-containing protein 7 (FBW7), also known as FBXW7, hCDC4, and AGO, is located at chromosome 4q31, which is a genomic region deleted in more than 30% of cancers." (PMID 36457505, 2022). "Although not all F-box proteins have good characteristics, many F-box proteins, such as SKP2, FBXW7, FBXO4, and FBXO32, are related to the cancer development and progression and cancer cachexia." (PMID 34950036, 2021). "Next, CNA analyses revealed that each gene is frequently altered in 10 common cancer types, and that SKP1, RBX1, FBXW7 and FBXO5 tend to exhibit more losses, while CUL1 and SKP2 exhibit more gains." (PMID 35008511, 2021). "The downregulation of FBXW7 leads to the synergistic accumulation of cellular and active chromatin-bound MYC in various types of cancer." (PMID 33494392, 2021). "Collectively, these data indicated that the effect of FBXW7 knockout on M2-like TAM polarization and on the cancer-promoting function of M2 macrophages was dependent on c-Myc." (PMID 33260160, 2020).